TMPRSS7 (transmembrane serine protease 7)
Description:
Serine protease which preferentially hydrolyzes peptides with Arg at the P1 position.
Tractability: Antibody: UniProt places it where antibodies can reach, with medium confidence; UniProt predicts a signal peptide or a membrane-spanning region; its Gene Ontology location is reachable by antibodies, with medium confidence.
Gene: Protein-coding gene on chromosome 3 (112,034,736 to 112,081,269, forward strand). Ensembl gene ENSG00000176040.
Subcellular location: Cell membrane
Gene Ontology:
Molecular function: serine-type peptidase activity; serine-type endopeptidase activity
Biological process: protein processing; proteolysis
Cellular component: plasma membrane
Genetic constraint (gnomAD): Loss-of-function variants: 56 observed, 66.77 expected, observed/expected ratio (o/e) 0.84, 90% interval 0.68 to 1.05. The upper end of that interval is the gene's LOEUF score, 1.05, which puts it in group 4 of 6, group 1 being the genes least tolerant of losing a copy. Missense variants: 756 observed, 805.11 expected, observed/expected ratio (o/e) 0.94, 90% interval 0.88 to 1. Synonymous variants: 293 observed, 289.88 expected, observed/expected ratio (o/e) 1.01, 90% interval 0.92 to 1.11.
Homologues: Orthologues: chimpanzee TMPRSS7 (99% identical), pig TMPRSS7 (90% identical), dog TMPRSS7 (90% identical), rabbit TMPRSS7 (90% identical), mouse Tmprss7 (88% identical), guinea pig TMPRSS7 (88% identical), rat Tmprss7 (87% identical), macaque TMPRSS7 (83% identical), Drosophila melanogaster Sb (17% identical), zebrafish tmprss7 (12% identical), Drosophila melanogaster CG17242 (6% identical). Paralogues in human: ST14 (31% identical), TMPRSS6 (25% identical), TMPRSS15 (23% identical), TMPRSS13 (18% identical), TMPRSS9 (17% identical), TMPRSS3 (15% identical), TMPRSS2 (15% identical), TMPRSS5 (15% identical), TMPRSS11E (14% identical), TMPRSS11F (14% identical), HPN (14% identical), TMPRSS11B (13% identical), and 5 more.
Diseases named in the same sentence as TMPRSS7 in open-access papers:
TMPRSS7 is named in the same sentence as 6 diseases in open-access papers, as found by Europe PMC text mining. Sharing a sentence is not in itself a finding about the gene and the disease. The quoted sentences say what the papers report.
breast carcinoma (2 papers, 2014 to 2025). "Our results show that the TMPRSS7 intronic variant rs2399403 associated with breast cancer survival." (PMID 25029565, 2014). "TMPRSS7 (matriptase-3) is very rarely studied with only one publication by Szabo and colleagues (2005) and has no known role in any cancer, but we found here that rs1844925 associated with breast cancer risk." (PMID 25029565, 2014). "Interestingly, TMPRSS7, encoding matriptase-3, was the only gene having SNPs associated with both breast cancer risk and prognosis." (PMID 25029565, 2014). "SNPs in TMPRSS3 (rs3814903 and rs11203200), TMPRSS7 (rs1844925), and HGF (rs5745752) associated significantly with breast cancer risk (Ptrend = 0.008–0.042)." (PMID 25029565, 2014). "TMPRSS3 SNPs rs3814903 and rs11203200, TMPRSS7 SNP rs1844925, and HGF SNP rs5745752 associated significantly with breast cancer risk (Poverall = 0.029, 0.008, 0.042, and 0.017, respectively)." (PMID 25029565, 2014). "More important, TMPRSS7 belongs to the same TTSP subfamily as matriptase and matriptase-2 that we have found to be associated with breast cancer, which makes it of interest for further study." (PMID 25029565, 2014). "To address this hypothesis, we genotyped tagging SNPs (tagSNPs) of five TTSP genes, TMPRSS1, TMPRSS2, TMPRSS3, TMPRSS7, and TMPRSS11E, two other serine proteases uPA and PRSS8, and HGF, and investigated their association with breast cancer risk and patient survival." (PMID 25029565, 2014). "No reports have described TMPRSS7 in breast tissue or breast cancer." (PMID 25029565, 2014).
atherosclerosis (1 paper, 2025). A disease characterized by the build-up of fatty material and calcium deposition in the arterial wall resulting in partial or complete occlusion of the arterial lumen. "Given the potential roles of TMPRSS7 in tumor growth and blood pressure regulation, the association of this gene with ischemic stroke may reflect an effect on atherosclerosis or blood pressure." (PMID 40385396, 2025).
ischemic stroke (1 paper, 2025). A stroke disorder caused by obstruction of blood flow to the brain, due to thrombotic (local blood clot formation) or embolic (due to a blood clot or other material traveling from another site) event. "Another study reported that rs147783135 of TMPRSS7 was related to ischemic stroke, with the minor T allele being protective against this condition." (PMID 40385396, 2025).
TMPRSS7 also shares sentences with these, for which no sentence is quoted: tumor (3 papers); cancer (2); invasive breast carcinoma (1).